GLO1 (glyoxalase I)
Diseases named in the same sentence as GLO1 in open-access papers (continued):
Sharing a sentence is not in itself a finding about the gene and the disease.
gastric cancer (5 papers, 2012 to 2025). A primary or metastatic malignant neoplasm involving the stomach. "Data from the present study demonstrated that upregulation of GLO1 in gastric cancer tissues is significantly associated with tumor progression and advanced stages of the disease." (PMID 22479608, 2012). "Elevated expression of GLO1 was significantly associated with gastric wall invasion, lymph node metastasis, and pathological stage, suggesting a novel role of GLO1 in gastric cancer development and progression." (PMID 22479608, 2012). "Our experiments clearly show that GLO1 is frequently over-expressed in gastric cancer and associated with cancer metastasis." (PMID 22479608, 2012). "Our data indicate that GLO1 regulates the activation of metastasis-associated signaling pathways in gastric cancer cells." (PMID 22479608, 2012). "Clinically, our results indicate that GLO1 is highly expressed in gastric cancer and significantly associated with tumor progression and advanced stages of the disease." (PMID 22479608, 2012). "Our results confirm over-expression of GLO1 in gastric carcinoma and its strong association with advanced stages and poor prognosis." (PMID 22479608, 2012). "The correlation between Glo1 copy number increase assessed by qPCR and poor survival in gastric cancers has been ameliorated." (PMID 35898868, 2022). "Clinicopathological Correlations of GLO1 expression and 5-year Survival Rate in 114 Gastric Cancer Patients." (PMID 22479608, 2012). "Based on these findings, we propose that GLO1 mediates gastric cancer cell migration and invasion at least partially mediated through activation of CXCL1, CXCL8, and VEGF." (PMID 22479608, 2012). "Over-expression of GLO1 in gastric cancer cell lines increases cell proliferation, migration and invasiveness." (PMID 22479608, 2012). "Our results collectively suggest that GLO1 positively regulates the migration and invasion abilities of gastric cancer cells." (PMID 22479608, 2012). "From our previous data, GLO1 upregulation was observed in gastric cancer specimens using cDNA microarray." (PMID 22479608, 2012). "In our experiments, levels of both HIF-1α and NF-κB were reduced in nuclei upon GLO1 silencing in gastric cancer cell lines, along with downstream target genes (VEGF, CXCL1, CXCL8, MMPs)." (PMID 22479608, 2012). "Expression of GLO1 was significantly higher in patients with more advanced pathologic stages (III/IV) of gastric cancer, compared to those in the earlier pathologic stages (I/II) (P = 0.001 and P<0.001 for qRT-PCR and IHC, respectively)." (PMID 22479608, 2012). "The expression of GLO1 was determined in primary gastric cancer specimens using quantitative polymerase chain reaction, immunohistochemistry (IHC), and western blotting analyses." (PMID 22479608, 2012). "Indeed, a significant correlation between GLO1 overexpression and tumor cell invasion, lymph node metastasis as well as reduced 5-year survival was reported for gastric cancer." (PMID 28549423, 2017). "Furthermore, alterations the expression of GLO1 in gastric cancer cell lines affects cell migration and invasion abilities." (PMID 22479608, 2012). "Our data strongly suggest that high expression of GLO1 in gastric cancer enhances the metastasis ability of tumor cells in vitro and in vivo, and support its efficacy as a potential marker for the detection and prognosis of gastric cancer." (PMID 22479608, 2012). "Our results provide direct evidence supporting the involvement of GLO1 in gastric cancer progression and the might through alternation of its downstream migration and invasion pathways." (PMID 22479608, 2012). "Among these genes, we focused on GLO1 as a molecular target for gastric cancer." (PMID 22479608, 2012). "The role of GLO1 in gastric cancer development or progression is currently unclear." (PMID 22479608, 2012). "Notably, expression of GLO1 is significantly higher in advanced stages of gastric cancer." (PMID 22479608, 2012).
gastric cancer (continued). "In the IHC study, a positive significant correlation between GLO1 and CXCL1 expression patterns was observed in resected specimens of gastric cancer." (PMID 22479608, 2012). "Our results confirmed high expression of GLO1 in advanced gastric cancer, compared to noncancerous gastric mucosa." (PMID 22479608, 2012). "Moreover, elevated GLO1 and concomitant CXCL1 over-expression in patients with gastric cancer were significantly correlated with survival." (PMID 22479608, 2012). "Data from qRT-PCR experiments revealed GLO1 overexpression (≥1.5-fold) in 51 (57.3%) of gastric cancer tissues, compared with noncancerous tissues." (PMID 22479608, 2012). "GLO1 expression was higher in gastric cancer tissues, compared with that in adjacent noncancerous tissues." (PMID 22479608, 2012).
lung carcinoma (5 papers, 2019 to 2025). "Together, these data confirm that inhibition of the glyoxalase system in lung cancer cells can promote accumulation of methylglyoxal-derived adducts, and that Glo1 loss can impair cell viability if methylglyoxal is present at high levels." (PMID 31811141, 2019). "In lung cancer, inhibition of GLO1 expression activity leads to MG accumulation, which can significantly inhibit tumor growth and induce cell apoptosis." (PMID 40352588, 2025). "To inhibit methylglyoxal detoxification genetically, we utilized CRISPR/Cas9-based genome editing to delete Glo1 from lung cancer cells." (PMID 31811141, 2019). "Though exogenous methylglyoxal can induce LGSH accumulation in parental lung cancer cells, levels of intracellular LGSH were dramatically lower in Glo1-deficient cells." (PMID 31811141, 2019). "To determine whether Glo1 expression contributes to lung tumor growth, we implanted parental lung cancer cells and Glo1-deleted cells subcutaneously as mouse allografts." (PMID 31811141, 2019). "Taken together, these data confirm that Glo1 is required for LGSH formation, and that this enzyme represents a major mechanism for methylglyoxal detoxification in lung cancer cell lines." (PMID 31811141, 2019). "Indeed, we found that when cultured in 0.5% oxygen, lung cancer cell lines accumulate higher levels of proteins containing MG-H1 adducts, especially in NSCLC lines that do not express Glo1." (PMID 31811141, 2019).
non-small cell lung carcinoma (5 papers, 2017 to 2025). A group of at least three distinct histological types of lung cancer, including non-small cell squamous cell carcinoma, adenocarcinoma, and large cell carcinoma. "When applied to erythrocytes and non-small cell lung carcinoma (NSCLC) cell lines, the method demonstrates that glucose alone can increase D-lactate production by up to 65% relative to L-lactate in a GLO1-dependent manner." (PMID 41221394, 2025). "Through their Glo1 inhibitor activity TLSC702 and piceatannol, a naturally occurring stilbene, reduce the proliferation of human non-small cell lung cancer cells expressing high Glo1 levels." (PMID 33869040, 2021).
ovarian carcinoma (5 papers, 2018 to 2025). A malignant neoplasm originating from the surface ovarian epithelium. "From the exploration of novel biomarkers like RAGE to the potential therapeutic implications of Glo1, ongoing research offers hope for improved diagnostic methods and targeted treatments, aiming for better outcomes in the battle against ovarian cancer." (PMID 38785990, 2024). "This implies that the development and spread of ovarian cancer are linked to elevated Glo1 expression." (PMID 38785990, 2024). "Thus, it seems that screening diagnosis of ovarian cancer should be supplemented by GLO1, TUFT1, and UBA2 determination and assessment of the risk of loss of adequate response to chemotherapy by GLO1 mRNA expression pattern determination." (PMID 35992817, 2022). "Encouragingly, more investigations are warranted to provide reliable data and unlock the mysteries surrounding Glo1 in ovarian cancer." (PMID 38785990, 2024). "Monica Brown Jones’ research discovered a significant level of Glo1 overexpression in invasive ovarian cancers compared to low-malignant potential ovarian tumors." (PMID 38785990, 2024). "Expression of several proteins appeared to be elevated in the FH-OSE cells, including Glo1, suggesting that high expression of Glo1 is related to the occurrence and progression of ovarian cancer." (PMID 35898868, 2022). "Among patients who lost adequate response to treatment, GLO1 expression was significantly higher than that among women with ovarian cancer responding to chemotherapy (p < 0.05)." (PMID 35992817, 2022). "Monica Brown Jones revealed a high degree of overexpression of Glo1 in invasive ovarian cancers compared with the low malignant potential ovarian tumors." (PMID 35898868, 2022). "This suggests that MGO accumulation in ovarian cancer may serve a protective role when BRCA2 is impaired, potentially impacting BRCA2 function and influencing ovarian cancer progression through Glo1 regulation." (PMID 40191206, 2025). "The exact mechanisms of Glo1 in ovarian cancer remain unknown, presenting an intriguing avenue for future research." (PMID 38785990, 2024). "The exact mechanisms of Glo1 in the ovarian cancer remain unknown and Glo1 may be used as a therapeutic target in the future." (PMID 35898868, 2022). "We noted that the mRNA of UBA2, GLO1, TUFT1, HPD, and GBF1 were upregulated in the ovarian cancer samples in comparison to the control samples." (PMID 35992817, 2022). "mRNAs corresponding to genes UBA2, GLO1, STATH, and TUFT1, were differentiated in the study samples, irrespective of the stage of ovarian cancer from the control samples, and we decided to focus on them in further analyses." (PMID 35992817, 2022).
Parkinson disease (5 papers, 2011 to 2025). A progressive degenerative disorder of the central nervous system characterized by loss of dopamine producing neurons in the substantia nigra and the presence of Lewy bodies in the substantia nigra and locus coeruleus. "However, as with our C9orf72 and sporadic ALS induced astrocytes, we found a consistent significant loss of GLO1 in the sporadic Parkinson’s disease cases compared to the sporadic Parkinson’s disease age and sex matched controls." (PMID 31647549, 2019). "Whether a gain-of-function of alpha-synuclein and other Parkinson triggering events also modulate the glyoxalase system, remains an issue we are investigating, and this seems credible in view of a report on altered glyoxalase I expression in mouse brains with Parkin deficiency." (PMID 21248374, 2011). "GLO1 is also a drug target of baicalein and indomethacin, which are emerging as preclinical candidates for Parkinson’s disease management." (PMID 40826483, 2025). "This loss of GLO1 in both familial and sporadic ALS samples as well as sporadic Parkinson’s samples may suggest a novel common pathway of dysfunction between the two neurodegenerative disorders." (PMID 31647549, 2019). "However, the fact that we found similar alterations in the GLO1 levels in SALS induced astrocytes and sporadic Parkinson’s disease cases suggests that an important novel common mechanism of dysfunction may exist between ALS and Parkinson’s disease." (PMID 31647549, 2019).
anxiety disorder (4 papers, 2012 to 2022). A category of psychiatric disorders which are characterized by anxious feelings or fear often accompanied by physical symptoms associated with anxiety. "Previous studies imply that the abnormality of certain genes is associated with anxiety disorders, such as CRHR1, FKBP5, CREB, Egr-1, Glo1, Gsr, AC8, CaMKIV, dystrophin, HTTLPR and COMT Met158." (PMID 22681774, 2012).
chronic kidney disease (4 papers, 2017 to 2022). Impairment of the renal function secondary to chronic kidney damage persisting for three or more months. "An abnormal increase in MG dicarbonyl stress is a characteristic of chronic kidney disease (CKD) and driven by the down-regulation of renal Glo1, which increases flux of MG-H1 formation." (PMID 35409010, 2022). "Promising strategies aimed at halting the vicious cycle between chronic kidney disease and increases in glycative stress include the suppression of AGE accumulation in the body and the enhancement of GLO-1 to strengthen the host defense machinery against glycative stress." (PMID 28106734, 2017). "Dicarbonyl stress and increased formation of MG-H1 represent key contributory factors of chronic kidney disease (CKD), likely as result of Glo1 downregulation in non-diabetic subjects." (PMID 31331077, 2019).
diabetic encephalopathy (4 papers, 2019 to 2021). A brain disease that is characterized by functional impairment of cognition, cerebral signal conduction, neurotransmission and synaptic plasticity, and underlying structural pathology associated with diabetes. "The improvement in diabetic encephalopathy using quercetin was established by citing the decrease in protein glycation, oxidative stress, and inflammation through the upregulation of Glo-1." (PMID 34206761, 2021). "Mounting evidence suggests that Glo-1 overexpression has a therapeutic effect on diabetic complications, including diabetic encephalopathy." (PMID 32982741, 2020). "Evidence verifies that the induction of Glo-1 leads to clear prophylactic and therapeutic effects on diabetic complications, including diabetic encephalopathy." (PMID 32982741, 2020).
liver cancer (4 papers, 2016 to 2025). An epithelial or non-epithelial malignant neoplasm that arises from the liver. "In their study aimed at functionally identifying tumor suppressor genes in liver cancer, Zender and collaborators identified GLO1 gene which knockdown using specific shRNAs increased tumor growth in a mouse model." (PMID 28117708, 2017). "On the other hand, a study aimed at functionally identifying tumor suppressor genes in liver cancer identified and validated GLO1 as a tumor suppressor gene which knockdown using shRNAs increased tumor growth in a mouse model." (PMID 27759563, 2016). "However, a functional screen in liver cancer identified GLO-1 as a potential tumor suppressor gene." (PMID 40727469, 2025).
lymph node metastasis (4 papers, 2012 to 2025). "LCP1 was correlated with lymph node metastasis and proposed as independent PC prognostic factor, while GLO1 might serve as a high-grade prostatic intraepithelial neoplasia marker and is strongly linked to early biochemical recurrence." (PMID 36818049, 2023).
myocardial infarction (4 papers, 2019 to 2024). Gross necrosis of the myocardium, as a result of interruption of the blood supply to the area, as in coronary thrombosis. "Complex interventions such as the overexpression of GLO-1 have already been carried out, which improved the detoxification of MG and also ameliorated the outcomes of acute myocardial infarction." (PMID 38999777, 2024). "For instance, overexpression of Glo1 in C57BL/6 transgenic mice was associated with reduced MG AGE levels and the mice exhibited superior cardiac function at 4 weeks post-MI (myocardial infarction) compared to wild-type mice." (PMID 33255888, 2020). "In addition, Glo1 transgenic mice are partially protected from myocardial infarction-induced cardiac dysfunction due to reduced cardiac inflammation and improved vascular density." (PMID 36093169, 2022).
Alzheimer disease (3 papers, 2020 to 2025). A progressive, neurodegenerative disease characterized by loss of function and death of nerve cells in several areas of the brain leading to loss of cognitive function such as memory and language. "The only other protein significantly upregulated in Alkbh7-/- was heme binding protein 1 (Hebp1), and notably a recent study found both GLO-1 and Hebp1 were upregulated in Alzheimer’s disease, suggesting these proteins may share a common upstream regulator." (PMID 32795389, 2020).
bladder cancer (3 papers, 2023 to 2025). "To further observed the role of GLO1 in miR-205-3p regulating bladder cancer, we firstly detected the effect of GLO1 expression on bladder cancer cells." (PMID 37814205, 2023). "The results demonstrated that the GLO1 down-regulated cells exhibited more apoptotic cells and inhibited proliferation, migration and invasion abilities, and over-expressed GLO1 showed conversed effects on bladder cancer cells." (PMID 37814205, 2023). "In present study, we observed the role of miR-205-3p in bladder cancer progression, and further identified that miR-205-3p inhibited bladder cancer by targeting GLO1." (PMID 37814205, 2023). "Then we confirmed that GLO1, a downstream target of miR-205-3p, mediated the effect of miR-205-3p on bladder cancer cells." (PMID 37814205, 2023). "Eventually, we confirmed that miR-205-3p inhibits the occurrence and progress of bladder cancer by targeting GLO1 in vivo by nude mouse tumorigenesis and immunohistochemistry." (PMID 37814205, 2023). "To clarify the potential mechanism by which miR-205-3p and GLO1 affect the biological functions of bladder cancer, we performed KEGG pathway enrichment analysis based on the transcriptome sequencing results." (PMID 37814205, 2023). "At the same time, IHC assay was performed and confirmed that miR-205-3p increased tumor tissues had stronger protein expression of GLO1 and Ki-67, which hinted that miR-205-3p is related to GLO1 expression and proliferation of bladder cancer." (PMID 37814205, 2023). "Moreover, we found P38/ERK signaling pathway participated in the procedure of GLO1 influencing bladder cancer." (PMID 37814205, 2023). "Taken together, miR-205-3p can negatively regulates GLO1 in bladder cancer cell." (PMID 37814205, 2023). "Furthermore, activation of P38/ERK reversed the effect of miR-205-3p and GLO1 on the proliferation and apoptosis of bladder cancer cells." (PMID 37814205, 2023). "GLO1 was highly expressed in T24 bladder cancer cells in gene and protein levels." (PMID 37814205, 2023). "In addition, we also detected GLO1 protein levels in bladder cancer patients with high and low miR-205-3p expression." (PMID 37814205, 2023). "Moreover, RT-qPCR and western blot showed that both gene and protein expressions of GLO1 were greatly reduced in miR-205-3p over-expressed bladder cancer cells." (PMID 37814205, 2023). "Moreover, up-regulating GLO1 could reversed the inhibitory effect of miR-205-3p on bladder cancer cells." (PMID 37814205, 2023). "In bladder cancer, superficial bladder cancer (SBC) exhibited higher GLO1 activity than invasive bladder cancer (IBC)." (PMID 40352588, 2025). "In a word, miR-205-3p inhibits proliferation and metastasis of bladder cancer cells by activating the GLO1 mediated P38/ERK signaling pathway and that may be a potential therapeutic target for bladder cancer." (PMID 37814205, 2023).
COVID-19 (3 papers, 2022 to 2023). A disease caused by infection with severe acute respiratory syndrome coronavirus 2. "To date, the underlying cause(s) for the reduction plasma Glo1 levels in plasma of COVID-19 patients that died remain poorly defined." (PMID 35680931, 2022). "In this study, we identified four genes, GLO1, GPR135, DYNLL2, and EPB41L3 that were strongly associated with azoospermia and COVID-19." (PMID 37283758, 2023). "Expression of rate-limiting Glo1 is negatively regulated by the inflammation oxidative stress, and hypoxia conditions that are commonly seen in COVID-19 patients." (PMID 35680931, 2022). "We found that plasma levels of glutathione, and Glo1 were significantly lower in ICU COVID-19 patients that died compared to ICU COVID-19 patients that survived." (PMID 35680931, 2022). "The increase in MG synthesis arising from upregulation of glycolysis coupled with decreases in free GSH and Glo1 levels should lead to accumulation of MG in blood and tissues of COVID-19 patients." (PMID 35680931, 2022). "Additionally, we also found a reduction of plasma levels of Glo1 protein in COVID-19 patients that died." (PMID 35680931, 2022). "Moreover, the expression level of GLO1 was also found to be higher in COVID-19 patients than in normal individuals." (PMID 37283758, 2023).